METTL16 (methyltransferase 16, RNA N6-adenosine)
Diseases named in the same sentence as METTL16 in open-access papers (continued):
Sharing a sentence is not in itself a finding about the gene and the disease.
tumor (continued). "In addition, given the role of METTL16 in regulating snRNA methylation and hence their processing, METTL16 dysregulation could favour tumour development by inducing changes in alternative splicing." (PMID 33461542, 2021). "By controlling MAT2A splicing and stability, METTL16 ensures that SAM levels remain balanced, which is essential for tumor cell survival and proliferation." (PMID 41459114, 2026). "For example, METTL16 has been shown to inhibit ferroptosis in HCC cells, promoting tumor progression, and its high expression correlates with poor prognosis in HCC patients." (PMID 40271153, 2025). "Conversely, regulators such as IGF2BP2, METTL16, and FTO demonstrated highly context-specific and sparse expression across tumor types." (PMID 40565233, 2025). "Functionally, METTL16 promotes CRC cell proliferation, migration, and invasion, and enhances in vivo tumor growth." (PMID 41322419, 2025). "In summary, METTL16 plays multifaceted roles in HCC by regulating CSC self-renewal, ferroptosis resistance, chemoresistance, metabolism, and lncRNA-mediated tumor suppression through both m6A-dependent and -independent mechanisms." (PMID 41322419, 2025). "In CCA, METTL16 is highly expressed in tumor tissues, and its knockdown significantly inhibits CCA cell proliferation and slows tumor progression." (PMID 41322419, 2025). "In PTC, METTL16 increases m6A abundance in SCD1, activates lipid metabolism, and inhibits tumor progression." (PMID 41256854, 2025). "In osteosarcoma, METTL16 targets vacuolar protein sorting protein 33b (VPS33B) for degradation, driving tumor progression." (PMID 41256854, 2025). "METTL16, an RNA m6A methyltransferase, has recently emerged as a critical regulator of the immune microenvironment in HCC, influencing tumor progression and response to immunotherapy." (PMID 39911396, 2025). "METTL16 is highly expressed in HCC, conferring resistance to ferroptosis and promoting cell viability and tumor progression." (PMID 41322419, 2025). "Recent evidence suggests that METTL16 also modulates the tumor microenvironment (TME), potentially affecting immune cell infiltration, immune checkpoint expression, and tumor immune evasion." (PMID 41322419, 2025). "METTL16 was recently identified as the second m6A writer, a novel ferroptosis repressor in HCC cells that can promote cell viability and tumor progression." (PMID 40386780, 2025). "Further experiments demonstrate that METTL16 knockout markedly suppresses HCC initiation and progression while exerting only minimal effects on normal liver development, indicating a tumor-selective role." (PMID 41322419, 2025). "Mechanistically, METTL16 promotes the expression and stability of ATF4, thereby suppressing ferroptosis in CC and ultimately accelerating tumor growth." (PMID 39744432, 2025). "Overexpression of METTL16 in CRC cells decreases the proportion of PD-1+ T cells, and when combined with PD-1 blockade, METTL16 overexpression synergistically inhibits CRC tumor growth in vivo." (PMID 41322419, 2025). "This aligns with previous findings that METTL16 can act as a tumor suppressor in some cancers, while CAPN2 drives tumor growth." (PMID 39434688, 2024). "This study aims to elucidate the role of METTL16, an m6A writer gene, in regulating core genes such as CAPN2 and MROH8, influencing tumor growth and metastasis." (PMID 39434688, 2024). "We observed significantly higher expression of METTL16, ITPR1, CAPN2, ITGA3, RAC1, ITGA6, and CHMP28 in tumor samples (P<0.05)." (PMID 39434688, 2024). "IHC and Oil Red O staining demonstrated that METTL16 knockdown increased SCD1, Ki-67, and TG staining in K1 tumor xenografts but decreased this parameter in cells treated with A939572." (PMID 38334797, 2024). "Functional assays demonstrated that METTL16 and YTHDC2 (an m6A reader) collaboratively enhanced MROH8 mRNA stability, thereby inhibiting CAPN2 expression and reducing tumor proliferation and metastasis (P<0.001)." (PMID 39434688, 2024).
tumor (continued). "Depletion of METTL16 significantly inhibited CCA cell proliferation and decreased tumor progression." (PMID 37817227, 2023). "In this study, we observed decreased level of METTL16 in clinical CRC tumor samples and CRC cell lines, compared with the non-tumor tissues and normal cell line." (PMID 37647025, 2023). "METTL16 enhanced cell proliferation, migration, and invasion, and promoted CRC tumor growth in vivo." (PMID 37647025, 2023). "We showed that depletion of METTL16 significantly inhibited CCA cell proliferation and decreased tumor progression." (PMID 37817227, 2023). "Taken together, these results demonstrate that METTL16 knockdown inhibited HCC cellular migration, invasion, and proliferation, and promoted HCC cellular apoptosis, indicating that METTL16 silencing has tumor-suppressive roles in HCC." (PMID 35596159, 2022). "METTL3, METTL14, METTL16, YTHDC1, YTHDC2, and ZC3H13 expression levels were significantly greater in tumor tissues (p < 0.05)." (PMID 36091006, 2022). "Blue background indicated the most significant genes down-regulated in tumor tissues, including YTHDC1, YTHDC2, METTL16, and FTO." (PMID 35581263, 2022). "As a non-classical RNA methyltransferase, METTL16 exerts multifaceted roles in cancer development and tumor immune regulation." (PMID 41322419, 2025). "Furthermore, METTL16 influences the TME, potentially affecting immune cell infiltration, immune checkpoint expression, and tumor immune evasion." (PMID 41322419, 2025). "Emerging evidence suggests that m6A regulators, such as METTL16, may interact with CAPN2 to influence tumor progression through post-transcriptional mechanisms." (PMID 39434688, 2024). "Interestingly, when METTL16 was knocked down while SYNPO2L was overexpressed, tumor growth and migration were similar to the control group." (PMID 39247832, 2024). "Furthermore, simultaneous overexpression of METTL16 and CAPN2 significantly increased tumor cell growth and proliferation (P<0.001)." (PMID 39434688, 2024). "The RNA level of PDL-1 in collected CRC tumor tissues is notably elevated, whereas the level of METTL16 is significantly decreased, compared with the non-tumor tissues." (PMID 37647025, 2023). "Collectively, these data demonstrate that METTL16 overexpression promoted HCC cellular migration, invasion, and proliferation, inhibited HCC cellular apoptosis, and promoted HCC tumor growth in vivo, indicating that METTL16 overexpression has oncogenic roles in HCC." (PMID 35596159, 2022). "In biological contexts where METTL16 promotes tumor progression through non-enzymatic mechanisms, such as eIF3-mediated translational regulation, complete protein degradation using PROTACs or molecular glues may be a more effective strategy." (PMID 41459114, 2026). "Similarly, the three writers, METTL3, METTL16, and ZC3H13 have all been shown to influence PTC progression, tumor size, and prognosis, and as the up- or down-regulation of the enzymes is associated with PTC, they may also be useful as biomarkers of disease." (PMID 40243425, 2025). "The function of METTL116 was further evaluated in the METTL16 knockdown and overexpression CRC xenografts, which indicated that overexpression of METTL116 elevated tumor growth, whereas suppression of METTL16 inhibited tumor growth, as reflected by tumor size, volume, and weight." (PMID 37340443, 2023). "Moreover, METTL16 knockdown led to increased expression of Ki-67 and PCNA, two proteins correlated with cancer cell proliferation, according to IHC staining, which was in line with the results of mouse tumor growth." (PMID 37182151, 2023). "As a novel m6A methyltransferase, METTL16 may regulate the expression of tumor- and immune-related genes, thereby modulating immune cell infiltration, cytokine secretion, and immune checkpoint regulation within the TME, ultimately affecting tumor growth and antitumor immune responses." (PMID 41322419, 2025).
tumor (continued). "Through spatial transcriptomic analysis of HCC patients, we observe high expression levels of METTL16, an enzyme responsible for RNA m6A modification, within HCC tumor regions compared to adjacent normal tissue or non-tumor regions." (PMID 38302992, 2024).
cancer (62 papers, 2018 to 2026). A tumor composed of atypical neoplastic, often pleomorphic cells that invade other tissues. "Recent studies have underscored the impact of METTL16 gene mutations in the development and progression of cancer, revealing several critical genetic alterations." (PMID 41459114, 2026). "METTL16 plays a crucial role in regulating key oncogenic signaling pathways and metabolic processes associated with cancer development and progression." (PMID 41459114, 2026). "METTL16 has been implicated in the regulation of the Wnt/β-catenin signaling pathway, a critical pathway involved in cancer initiation, progression, and metastasis." (PMID 41459114, 2026). "Aberrant expression of METTL16 is closely linked to cancer cell proliferation, invasion, metastasis, and drug resistance, through modulation of RNA metabolism." (PMID 41459114, 2026). "The activity and function of METTL16 protein can be influenced by various translational modifications, post-translational modifications, and genetic mutations, which in turn impact cancer development and progression." (PMID 41459114, 2026). "Lastly, most cancer-associated mutants were able to bind and methylate U6 snRNA similar to full-length METTL16, except METTL16, G110C, and R241Dfs*2, which decreased methylation by 113-fold or more." (PMID 41007290, 2025). "Recent studies have demonstrated that aberrant expression of METTL16 is closely associated with clinical prognosis across multiple cancer types." (PMID 41322419, 2025). "Another consideration is how METTL16 cancer-associated mutants participate in methylation-independent functions and/or alterations in other genes, such as MTAP." (PMID 41007290, 2025). "Our kinetic analysis of METTL16 cancer-associated mutants identified one mutant, METTL16 R200Q, with increased catalytic efficiency, which is consistent with this mutant showing enhanced methylation activity in previous cell-based assays." (PMID 41007290, 2025). "METTL16, a newly discovered m6A methyltransferase, is also associated with various malignant characteristics in different cancers and exhibits reduced expression levels in PTC tissues." (PMID 38334797, 2024). "Previous studies have shown that METTL16 expression is associated with several diseases, including cancer." (PMID 39101773, 2024). "The underlying molecular mechanism mainly involves METTL16 functioning as an m6A methyltransferase to promote cancer cell proliferation." (PMID 38045858, 2023). "Further research is needed to elucidate the molecular mechanisms underlying these effects and to explore the potential of METTL16 as a therapeutic target for cancer treatment." (PMID 38045858, 2023). "METTL16 was first found to have a close correlation with a cancer-promoting long non-coding RNA: metastasis-associated lung adenocarcinoma transcript 1 (MALAT1)." (PMID 33362863, 2020). "Previous studies have proven METTL16 been linked with some types of cancers." (PMID 40015977, 2025). "Several cancer‐associated mechanisms have been proposed for METTL16." (PMID 38084791, 2024). "Several reports have also implicated METTL16 in certain types of cancers." (PMID 37927399, 2023). "This is intriguing as METTL16 overexpression has been implicated in a number of cancer types." (PMID 37504262, 2023). "Thus far, the mechanisms underlying upregulation of METTL16 in cancer remain unexplored." (PMID 37817227, 2023). "This review provides a detailed examination of METTL16's functions and regulatory mechanisms in cancer, emphasizing its m6A-dependent and m6A-independent roles in regulating RNA stability and function." (PMID 41459114, 2026). "These insights into METTL16's role in SAM metabolism highlight its relevance in cancer biology and underscore its potential as a therapeutic target." (PMID 41459114, 2026). "A recent study identified METTL16 as the most crucial METTL protein for cancer survival out of 25 METTLs." (PMID 41459114, 2026).
cancer (continued). "Accumulating evidence has indicated that METTL16 plays a pivotal role in the progression of various cancers by regulating cell proliferation, apoptosis, metastasis, and resistance to chemotherapy." (PMID 41695366, 2026). "In conclusion, METTL16 plays a dual role in cancer, with its prognostic significance depending on the expression level and alterations in specific tumors, subtypes, and even individual patients." (PMID 41459114, 2026). "Despite extensive research into various RNA-modifying enzymes in cancer, the specific roles and mechanisms of METTL16 remain inadequately understood." (PMID 41459114, 2026). "Inhibiting METTL16 or its downstream pathways presents a promising strategy for cancer therapy, particularly in cancers where METTL16 acts as an oncogene." (PMID 41459114, 2026). "The versatility and adaptability of METTL16 in different tumors underscore its central role in cancer cell adaptation and survival." (PMID 41459114, 2026). "These divergent expression patterns emphasize the complexity of METTL16's role in cancer and its potential as a prognostic biomarker for patient stratification and treatment decisions." (PMID 41459114, 2026). "In cancer, where cellular methionine dependency is often elevated, METTL16's regulation of SAM levels through MAT2A mRNA splicing becomes particularly important." (PMID 41459114, 2026). "This down-regulation of PMEPA1 inhibits the proliferation of bladder cancer cells and enhances their sensitivity to cisplatin, highlighting the potential of targeting METTL16 in cancer therapy." (PMID 41459114, 2026). "Lactylation also affects METTL16's activity and stability, modulating cancer cell responses to environmental stimuli." (PMID 41459114, 2026). "METTL16 exerts regulatory functions in cancer through m6A-independent mechanisms, involving direct interactions with RNA transcripts or proteins." (PMID 41459114, 2026). "The expression patterns of METTL16 have been extensively studied across various cancer types, revealing its dual role in clinical outcomes." (PMID 41459114, 2026). "Despite extensive research on RNA-modifying enzymes, the specific mechanisms and roles of METTL16 in cancer remain poorly understood." (PMID 41459114, 2026). "This article aims to comprehensively summarize the role and regulatory mechanisms of METTL16 in cancer, emphasizing its m6A-dependent and m6A-independent functions in the regulation of RNA function and stability." (PMID 41459114, 2026). "BACKGROUND: N6-methyladenosine (m6A) is the most abundant post-transcriptional modification, and METTL16 has recently emerged as a pivotal m6A methyltransferase in cancer." (PMID 41845506, 2026). "Because METTL16 has such diverse cellular roles, its direct role in cancer is likely mechanistically complex." (PMID 41007290, 2025). "Collectively, these findings reveal the expression patterns and biological functions of METTL16 across cancers, providing evidence for its utility as a prognostic biomarker and highlighting its critical role in CRC." (PMID 41322419, 2025). "To explore the expression state of METTL16 among various cancer types in a pan-cancer analysis, we concluded survival status, the subcellular distribution, genetic alteration and relevant molecular pathways." (PMID 40015977, 2025). "By regulating the malignant phenotype of GC cells at transcriptional and post‐transcriptional levels, METTL16 presents novel possibilities for cancer diagnosis and targeted therapy." (PMID 40095756, 2025). "Clinical studies and animal models indicate that aberrant METTL16 expression correlates with cancer prognosis, and its molecular functions offer opportunities for the development of targeted therapies and diagnostic biomarkers." (PMID 41322419, 2025). "We found that compared with normal tissues, METTL16 gene expression showed high expression in some cancers, but low expression in the rest of the cancers from the database." (PMID 40015977, 2025).